YY1 (YY1 transcription factor)
Diseases named in the same sentence as YY1 in open-access papers (continued):
Sharing a sentence is not in itself a finding about the gene and the disease.
breast cancer (continued). "However, the prognostic role of YY1 in breast cancer remains controversial." (PMID 41009346, 2025). "Moreover, lncRNA long intergenic non-protein coding RNA 958 (LINC00958) was also reported to be upregulated in BC tissues and could promote breast cancer tumorigenesis via the miR-378a-3p/YY1 axis." (PMID 37069649, 2023). "However, it is still unknown whether YY1 expression has any prognostic significance in patients with breast cancer." (PMID 37444605, 2023). "Concerning NF-kB signaling, often activated in inflammation-related cancers, it may repress miR-29a/b1 promoter activity directly in several tumors, as in breast cancer, or indirectly, by activating the transcription suppressor Yin Yang 1 (YY1), as in rhabdomyosarcoma." (PMID 36140539, 2022). "In addition, YY1 contributes to endocrine resistance and chemoresistance of breast cancer cells." (PMID 35103856, 2022). "However, the regulatory mechanisms for YY1 degradation and downstream target genes of YY1 in breast cancer cells are still largely unknown." (PMID 35103856, 2022). "YY1 depletion could block breast cancer cell proliferation and inhibit xenograft tumor formation." (PMID 35406384, 2022). "Importantly, overexpression of YY1 enhanced tumor aggressive growth in a mouse breast cancer model." (PMID 35811688, 2022). "Importantly, YY1 expression levels correlate with the presence of breast cancer." (PMID 33728560, 2021). "In addition, several studies report that a high expression of YY1 may be beneficial in the prognosis of breast cancer." (PMID 34457116, 2021). "Finally, we determined that the transcription factor Yin Yang 1 (YY1) could activate LINC00673 transcription in breast cancer cells." (PMID 31623640, 2019). "However, the function of YY1 in breast cancer remains controversial." (PMID 31623640, 2019). "We then investigated whether YY1 bound to the FEN1 promoter region in MCF7 breast cancer cells by conducting a chromatin immune-precipitation-PCR (ChIP-PCR) and showed that the FEN1 promoter was specifically pulled-down by an YY1-specific antibody but not the control antibody." (PMID 25885449, 2015). "RNF144A targets YY1 for proteasomal degradation to decrease the production of GMFG, hence acting as a tumor suppressor in breast cancer." (PMID 38313020, 2024). "These include EMT (TWIST1, SNAIL1, RUNX1, RUNX2, HIF1, and NOTCH1), breast cancer maintenance (OCT4, SP1, GATA1, ATF1, FOXO3a, ELK1, VDR, and NRF1), pro-metastatic responses (SMAD2/3, HNF1a, GLI1, NANOG, YY1, MYB1, and AP1), and immune modulation (STAT1/3)." (PMID 38398186, 2024). "Another study has shown that YY1 positively induces expression of BRCA1, a tumor suppressor, leading to tumor inhibition in breast cancer." (PMID 37444605, 2023). "YY1 upregulates the LINC00673 promoter, which targets miR-515-5p and, in turn, increases tumor cell growth by disrupting the breast cancer cell cycle and apoptosis." (PMID 37686541, 2023). "Thus, this study aimed to investigate the clinicopathological characteristics of YY1 expression and its association with survival outcomes independently and in connection with CP2c expression using formalin-fixed paraffin-embedded (FFPE) tissue blocks from patients with primary breast cancer." (PMID 37444605, 2023). "RUVBL1 and YY1 promote tumor growth, and inhibiting RUVBL1 expression in metastatic breast cancer cells can reduce both cell proliferation and invasion." (PMID 38020889, 2023). "In another study, it was found that the YY1 transcription factor activates the activator protein 2-alpha (AP-2α) activity on the oncogenic promoter ERBB2, which is found in several breast cancer tumors." (PMID 37686541, 2023).
breast cancer (continued). "Subsequently, we used the ROC plotter tool to analyze the relationship between YY1 (and PEBP1) expression and sensitivity in endocrine therapy, anti-HER2 therapy, or chemosensitivity in breast cancer." (PMID 37894300, 2023). "Herein, our findings established a novel YY1‐assisted DDX3X‐KTN1 regulatory axis, which would shed some light on the signaling involved in cell invasion and progression in breast cancer and open an avenue in finding novel therapeutic targets for breast cancer." (PMID 35811688, 2022). "NF-kB exerts an inhibitory effect on miR-29b2/c transcription also in breast-cancer-derived cells MCF7 and MDA-MB-231 by inducing the recruitment of YY1 onto the miR-29b promoter." (PMID 36140539, 2022). "The histidine cluster in the AD of YY1 compartmentalizes BRD4, MED1, and enhancer elements in phase-separated condensates to activate FOXM1 expression in breast cancer." (PMID 35740532, 2022). "YY1 also exerts a bidirectional effect in breast cancer, and although understanding the mechanism by which YY1 plays opposite roles in a specific type of cancer is difficult, whether the specificity of different YY1 interactors in different tumor stages determines the function of YY1 is unclear." (PMID 33985581, 2021). "The low expression level of POU5F1 and YY1 and high expression level of HEY1, IFNA13, NKX2-3, and NR2F1 were significantly related to poor prognosis in breast cancer." (PMID 34457116, 2021). "To validate the regulation of YY1 on METTL8 transcription in breast cancer, we tested the expression level of METTL8 mRNA in silenced YY1 conditions." (PMID 34063990, 2021). "In summary, this study revealed that FAM3C, YY1 and HSF1 are coordinated to promote the proliferation and migration of human breast cancer MDA‐MB‐231 cells." (PMID 30887707, 2019). "Downstream of TGF-β signaling YY1 enhances HSF1 expression and promotes proliferation and migration of breast cancer cells." (PMID 31824839, 2019). "FAM3C activates YY1 to induce HSF1 expression, which finally triggers the proliferation and migration of breast cancer cells by activating Akt." (PMID 30887707, 2019). "This study determined the role and mechanism of YY1 and HSF1 in FAM3C‐induced proliferation and migration of breast cancer cells." (PMID 30887707, 2019). "Clearly, the roles of FAM3C, YY1 and HSF1 in the pathogenesis of breast cancer and/or other cancers should be considered as a whole." (PMID 30887707, 2019). "In human MDA‐MB‐231 breast cancer cell line, transforming growth factor‐β (TGFβ) up‐regulated FAM3C, HSF1 and YY1 expressions." (PMID 30887707, 2019). "YY1 was shown to directly activate HSF1 transcription to promote the proliferation and migration of breast cancer cells." (PMID 30887707, 2019). "YY1 silencing blunted FAM3C‐ and TGFβ‐triggered activation of HSF1‐Akt‐Cyclin D1 pathway, and proliferation and migration of breast cancer cells." (PMID 30887707, 2019). "FAM3C up‐regulates YY1 to induce HSF1 expression, finally activating Akt‐Cyclin D1 pathway to promote the proliferation and migration of breast cancer cells." (PMID 30887707, 2019). "An increase in FAM3C expression due to excessive TGFβ production plays important roles in inducing YY1 and HSF1 expressions as observed in human breast cancer or other cancer tissues." (PMID 30887707, 2019). "We proved that G9a operates as a negative regulator of HEPH expression via YY1 and HDAC1 interaction, and is recruited to the HEPH promoter during breast cancer cell growth." (PMID 28819251, 2017). "We observed an increase of YY1 protein expression level in MDA-MB-231 and MCF-7 cells compared with MCF-10A cells; while YY2 expression level in breast cancer cell lines was robustly decreased." (PMID 28903375, 2017). "Next, to further confirm the different expression profiles of YY1 and YY2 in normal and tumor cells, we compared the expression levels of YY1 and YY2 in normal mammary epithelial cell line (MCF-10A) and breast cancer cell lines (MCF-7 and MDA-MB-231)." (PMID 28903375, 2017).
breast cancer (continued). "Under nutrient starvation condition, YY1 suppressed miR-372 expression, leading to SQSTM1/p62 expression and subsequent autophagy in breast cancer cell lines." (PMID 28459042, 2017). "To elucidate the role of YY2 in tumorigenesis, we first compared the expression levels of YY1 and YY2 in human clinical breast carcinoma tissues and the corresponding normal adjacent tissues." (PMID 28903375, 2017). "Further analysis to explain the functional consequences of POLQ c.-1060GG on YY1-mediated POLQ expression and on breast cancer progression are warranted." (PMID 25409685, 2014). "YY1 also reportedly activates the expression of human epidermal growth factor receptor 2 (ERBB2), which is overexpressed in approximately 30% of breast cancers and correlates with poor prognosis." (PMID 24674326, 2014). "We demonstrated, for the first time, the implication of AP-2α in combination with its cofactor, YY1, in ERBB2 oncogene overexpression in breast tumors both in vitro and in breast cancer tissue specimens." (PMID 18218085, 2008). "RNF144A promotes ubiquitination degradation of YY1, inhibits tumor cell proliferation and migration, and promotes ubiquitination degradation of HSPA2, and these mechanisms lead to the inhibition of breast cancer by RNF144A." (PMID 40756570, 2025). "Depletion of YY1 suppresses clonogenicity, migration, invasion, and tumor formation in breast cancer cells; ectopic YY1 expression in non-tumorigenic epithelial cells can enhance their migration and invasion capabilities." (PMID 40867231, 2025). "Furthermore, YY1 binds to the BRCA1 promoter and increases its expression of BRCA1 and other downstream genes in breast cancer." (PMID 39796650, 2024). "The top significant regulatory TFs (YY1, FOXC1, FOXL1, and MEF2A) may be responsible for the related pathways of the breast cancer cellular process of disease development." (PMID 39656775, 2024). "Several studies reported that the expression and regulatory roles of CP2c and YY1 might affect the development of cancer individually; however, the association between the interaction of these proteins and the prognosis of patients with breast cancer has not yet been investigated." (PMID 37444605, 2023). "YY1 overexpression could reverse the decrease of glucose uptake, lactate production, ATP release, HK2, and LDHA proteins in circYY1 depletion breast cancer cells." (PMID 37060064, 2023). "In conclusion, YY1 overexpression is a favorable prognostic biomarker in patients with breast cancer, and it has a negative correlation with CP2c at the protein level." (PMID 37444605, 2023). "YY1 overexpression is a favorable prognostic biomarker in patients with primary breast cancer, and it has a negative correlation with cofactor, CP2c at the protein level." (PMID 37444605, 2023). "Interestingly, hypoxia-induced Yin and Yang 1 (YY1) transcription factor works as a transcriptional activator of VWF, which in turn promotes angiogenesis and breast cancer cell migration." (PMID 37583933, 2023). "Conversely, YY1 protein levels were not much different between the breast cancers and the adjacent normal tissues, indicating another regulatory mechanism is functional at the post-transcriptional level." (PMID 37444605, 2023). "For example, in breast cancer cell lines, YY1 facilitates p27 ubiquitination and its negative interaction with p27 causes increased tumor growth." (PMID 37686541, 2023). "Overall, these findings suggest that YY1 and PEBP1 CNVs might play a specific role in immune infiltration in breast cancer." (PMID 37894300, 2023). "The transcription factors YY1 and AP-2 were previously associated with HER2 mRNA expression in breast cancer samples without HER2 amplification." (PMID 36383805, 2022). "Furthermore, neural network-based deep learning models were established to predict breast cancer cell types using BCPRS-related genes (HEY1, IFNA13, NKX2-3, NR2F1, POU5F1, and YY1)." (PMID 34457116, 2021).
breast cancer (continued). "We also have analyzed 60 breast cancer samples by immunohistochemistry (IHC) and found FGFR2 is negatively correlated with YY1 and BRCA1, suggesting that YY1 could be responsible for BRCA1 reduction in response to FGFR2 activation." (PMID 34514747, 2021). "YY1 is highly expressed in breast cancer and cooperates with activator protein to stimulate the expression of ERBB2 (Her2/neu), a proto-oncogene overexpressed in approximately 30% of breast cancers." (PMID 34063990, 2021). "In human breast cancer tissues, FAM3C, YY1 and HSF1 protein expressions were increased." (PMID 30887707, 2019). "Furthermore, we demonstrated that the interaction of YY1 protein with NMI and its involvement in NMI-mediated transcriptional regulation of hTERT in breast cancer cells." (PMID 28492540, 2017). "Tier two, characterized by high YY1 and low SOX2, is found in skin, testis and breast cancers." (PMID 27225481, 2016). "Moreover, YY1 enhances AP-2α, AP-2β, and AP-2γ transcriptional activity on the ERBB2 promoter in breast cancer cells." (PMID 18218085, 2008). "Indeed, we have previously shown that YY1 is able to enhance AP-2α, AP-2β, and AP-2γ transcriptional activity in vitro and that it is recruited via AP-2 to the ERBB2 endogenous promoter in a breast cancer cell line." (PMID 18218085, 2008). "Moreover, we showed that at least two mechanisms can lead to pathological ERBB2 overexpression in breast cancer: ERBB2 gene amplification and increased transcription through high levels of transcriptional activators, such as AP-2α and YY1." (PMID 18218085, 2008). "Studies demonstrate that YY1 functions as a transcriptional repressor of FEN1, and YY1 dissociates from the FEN1 promoter to increase its expression under DNA-damaging agent (mitomycin and taxol) treatment, consequently promoting resistance to drugs in breast cancer cells." (PMID 40867514, 2025). "In the patients with YY1 high tumor tissue, YY1 mRNA levels in breast cancers were significantly correlated with those in the adjacent normal cells, suggesting that the prognostics of breast cancers are primarily determined by the innate YY1 transcription status in the breast tissue." (PMID 37444605, 2023). "Although it has been suggested that STAT3 is the regulator of METTL8 gene expression in mouse embryonic development, it is an important result of showing that METTL8 expression in humans, especially in breast cancer conditions, is caused by not STAT3, but the YY1 transcription factor." (PMID 34063990, 2021). "The difference of EZH2 and YY1 expression between tumorigenic and nontumorigenic cells could explain the differential inhibitory effects of the two peptides in breast cancer cells and MCF-10A cells." (PMID 34065631, 2021). "Yin Yang 1 (YY1) is a member of the GLI‐Kruppel class of zinc finger DNA‐binding proteins and ubiquitously distributed in eukaryotic cells, which can act as transcriptional activators in several types of cancers, such as lung adenocarcinoma (LUAD), breast cancer, colon and prostate cancer." (PMID 32557953, 2020). "However, when tested in vivo, occupancy by YY1 was only observed in a prostate cancer cell line (1542-CP) but not in a breast cancer cell line (MCF-7) raising the possibility that the presence of YY1 prevents the establishment of a DHS." (PMID 21814516, 2011). "Although YY1 is not directly known to prompt the initiation of genomic instability, YY1 is a remarkable predictor of the outcome of breast cancer clonal selection, particularly in estrogen receptor (ER)-positive breast cancer patients undergoing hormone therapy." (PMID 32226547, 2020). "However, the mechanism of YY1 down regulation in breast cancer was not clear from this study." (PMID 31824839, 2019). "Using chromatin immunoprecipitation (ChIP) we also confirm that the identified YY1 site is occupied in vivo in the prostate cancer cell line 1542-CP, but not in MCF-7 breast cancer cells." (PMID 21814516, 2011).
breast cancer (continued). "In the present study, ERBB2 expression was also associated with combined high levels of AP-2α and its partner YY1 both in primary breast tumors, markedly in the absence of ERBB2 gene amplification, and in a breast cancer cell line." (PMID 18218085, 2008).